TNF (tumor necrosis factor)
Diseases named in the same sentence as TNF in open-access papers (continued):
Sharing a sentence is not in itself a finding about the gene and the disease.
infection (continued). "Furthermore, in support of the less distinct wasting symptoms observed at day 6 following infection of mice from the clove EO versus the placebo cohort, lower TNF-α, IL-6, and MCP-1 concentrations were measured in serum samples taken from the former versus the latter." (PMID 33807493, 2021). "Anti-TNF-α cessation before the third trimester did not influence infection risk, however, this outcome may also be biased by parental counselling." (PMID 33046558, 2021). "Therefore, implementing guidelines for latent tuberculosis infection screening and (prophylactic) treatment before starting anti-TNF therapy could lower infection rates." (PMID 34790122, 2021). "Hence, while the low dose elicits an earlier TNF-α response that then remains at similar levels up till 3 weeks post infection, the same response is slower to develop in the higher dose but more robust as the infection progresses." (PMID 34484203, 2021). "Due to the limitations of plasma transfusion, researchers are now focusing on developing neutralizing antibodies against virus particles along with immuno-modulation of cytokines like IL-6, Type I interferons (IFNs), and TNF-α that could help in combating the infection." (PMID 32849654, 2020). "After stratifying by Plasmodium infection density, submicroscopic infection was associated with increased peripheral concentrations of IFN-α and decreased concentrations of IL-6, while microscopic infections were associated with elevated levels of TNF, IL-10 and IL-5." (PMID 32365058, 2020). "However, TNF-α protein level in culture supernatants of PRRSV-infected cells was slightly more than that in culture supernatants of mock cells at any time point post-infection." (PMID 32046249, 2020). "Furthermore, biological therapies may increase the incidence of post-operative infections, especially anti-TNF therapy prior to surgery." (PMID 32269571, 2020). "Thus, it is practical to imagine that this inflammatory pathway might be modified due to infection, since the more silent the infection, the more successful it is, and TNFα signaling leads to an inflammatory response that can destroy all parasites." (PMID 31906500, 2020). "Finally, a marked increase in inflammatory chemokines MIP-1β/CCL4, MCP-1/CCL2, and IL-8/CXCL8, accompanied by an increase of inflammatory cytokines IL-15, IL-12, TNF-a, GM-CSF, and G-CSF, which was detected in the lung predominantly at day 7–9, the middle and late stage of infection." (PMID 33180882, 2020). "Indeed, high TNF-α levels may actually promote granuloma dissemination, infection progression and increased pathology." (PMID 33604556, 2020). "In addition, we found that pro-inflammatory cytokines exceed anti-inflammatory cytokines during leukocyte recovery and that low IL-8, MIP-1α, MIP-1β, MCP-1, and TNF-α expression at the beginning of the febrile episodes seem to hint at a more severe clinical course of the infection." (PMID 32519027, 2020). "Therefore, we determined the production of TNF-α, IL-1β and IL-1ra in the lungs after infection." (PMID 32517114, 2020). "TNF-α is associated with weight loss after infection but not with changes in the gut microbiota." (PMID 32071269, 2020). "Similarly, the evolution of the infection process in dogs may be determined correlating the parasite load with the TNF-α and IL-10 level in the spleen." (PMID 32983013, 2020). "Protection against active TB is known to require a clearly delineated T-helper type 1 (Th1) response, mediated by interferon-gamma (IFNγ), interleukin-2 (IL2), and tumor necrosis factor-alpha (TNFα), which may clear infection or drive it into an immune-mediated containment or latency." (PMID 32498074, 2020). "In contrast, infection of polarized monolayers with live bacteria does affect the isoelectric properties of epithelial cell monolayers, possibly by inducing TNFα expression, suggesting that there could be additional HbhA-independent mechanisms of barrier disruption." (PMID 32161724, 2020).
infection (continued). "Similarly, IL-6 and TNF-α gene expression results (respectively) corroborated those of iNOS with the lowest values consistently reported for cells preconditioned with nicotine prior to infection." (PMID 32370298, 2020). "However, upon the tail vein injection of HA‐HuR expression plasmid in infected animals, the expression levels of cytokines IL‐10 dropped while the TNF‐α expression had increased in liver, and interestingly, infection levels measured by Ld kinetoplastid DNA content dropped in mouse liver." (PMID 32031337, 2020). "Furthermore, we also showed that cytokines such as IL-1β, IL-6, TNF-α, IL-8, and IL-10 may act as indicators of a lethal outcome at the endpoint of the infection process." (PMID 33553280, 2020). "Significantly higher levels of IFN-γ and TNF-α cytokine-secreting CD4 T cells were generated upon M2e in vitro stimulation of the airway BAL cells from all LAIV-vaccinated mice at day 5 post-challenge infection compared to naïve mice as determined by flow cytometry ICS analysis." (PMID 33153089, 2020). "Although TNF-α and IFN-γ may have a vital cell-protective property or initiate protective immune responses in goats with CCPP, their blood levels may be linked to the severity of the MCCP infection amount of mycoplasma in the host." (PMID 33240679, 2020). "Others have suggested that TNF-α inhibition may directly or indirectly increase the rate of infection by organisms implicated in noncaseating granuloma formation." (PMID 32337619, 2020). "Importantly, in these cases CCL3 is essential for protective mechanisms involving the recruitment of effector CD8+ T-cells and macrophages to the sites of infection, robust early production of cytokines (TNF and IFNγ), induction of cytolytic activity and generation of radical oxygen intermediates." (PMID 32194558, 2020). "However, TNFα was released by antigen-stimulated cultures in response to N across the cohort spectrum from those with laboratory confirmed infection to uninfected HCW and pre-pandemic controls, presumably reflecting an amplified response from other cell types including macrophages and NK cells." (PMID 33361161, 2020). "Similarly, the proportion of infection-elicited TNFα+, IL2+ and polyfunctional CD4+ T-cells was significantly higher among influenza A/H3N2-infected (p = 0.038, 0.017 and 0.041 respectively) and influenza B-infected patients (p = 0.002, 0.048 and 0.004 respectively) than in vaccine recipients." (PMID 32572168, 2020). "Infection of peripheral monocytes activated endothelial cells in a TNF dependent manner, suggesting increased monocyte infection may lead to enhanced levels of TNF, driving more severe clinical disease." (PMID 33224897, 2020). "In addition, the patients infected with TM have previously been reported to have higher TNF-α, IL-1β, IL-12, and IL-10 levels in vivo, and the infection of TM enabled the enhancement of the production of cytokines such as TNF-α, IL-1β, IL-6, and IL-12 by stimulating macrophages in vitro." (PMID 33488545, 2020). "Additionally, it has been reported that HIV-specific CD4 T-cell responses (IFN-γ, IL-2, TNF-α) during early infection or untreated infection may predict disease progression and effective viral control." (PMID 32941433, 2020). "IL-1 and TNF-α are major inflammatory cytokines and are involved in both local and systemic immune responses through stimulating neutrophil leukocyte chemotaxis from the peripheral bloodstream to the mammary tissue where they arrive several minutes after the onset of infection." (PMID 32256195, 2020). "Although Tem cells are less proliferative and could not persist for a long term, they are ready to provide immediate protection at infection sites via producing multiple cytotoxic molecules, including granzyme B (Gzmb), perforin, interferon gamma (IFNγ), tumor necrosis factor (TNF), etc.." (PMID 32983095, 2020).
infection (continued). "Interestingly, a marked increase of TNFα was observed for the highly pathogenic 93/783 5 days post infection, but this increase was absent in Torö at the same time point." (PMID 32988388, 2020). "Furthermore, IV PR8-M infection provoked TNFα protein expression 32 hpvi." (PMID 33333815, 2020). "In addition to being a major stimulator of apoptosis, TNF-α together with IL-1β are proinflammatory cytokines expressed by PBMCs obtained from normal or B. pseudomallei -infected humans stimulated by infection or LPS, or in cells from B. pseudomallei infected mice." (PMID 32835600, 2020). "Likewise, the chimera promoted the strongest CD8+ T cell response after infection, but shared its predominance with the F3 vaccine, for the frequencies of single producers of IL-2 and double producers of TNF-α and IL-2, and TNF-α and IFN-γ and multifunctional CD8 T cells." (PMID 31024556, 2019). "The activation of NF-κB and expression of TNF-α at the infection site in C. albicans-infected fish, combined with the qPCR data showing that the chemokines CXCL8 and CCL2 were upregulated only in C. albicans infection, suggested that phagocytes might be recruited only to C. albicans infections." (PMID 31088918, 2019). "However, TNF-α levels after treatment with T6 were lower than the untreated control which may be related to the failure of T6 alone to control the infection, despite the increase IFN-γ." (PMID 31882925, 2019). "Many molecules derived from inflammatory cells and extracellular matrix like TNF-α, IL-8, C5a and fibronectin fragments have chemotactic activity on parasites and it has been considered that they play an important role in intestine invasion and the spread of infection to other organs." (PMID 30979831, 2019). "However, simultaneous expression of PA-X and PB1-F2 enhanced the expression level of IL-18 and TNF-a during the early infection period, although individual expression of full-length PA-X or PB1-F2 could decrease the expression level of these two genes." (PMID 31552197, 2019). "In addition, a study reported that the risk for malignant neoplasms and infections among patients aged > 65 years who received anti-TNF agents was 4.7 times higher than those among non-elderly patients." (PMID 31025187, 2019). "Indeed, infection with the vaccinia virus (VV), a poxvirus strain, sensitizes the cells to TNF- induced necroptosis, while the RIPK1 or RIPK3 deficient cells are resistant to the TNF-induced necroptosis." (PMID 31509938, 2019). "In response to infection or neuronal tissue damage, microglia rapidly alter their morphology and increase phagocytic activity, initiating an innate immune response by secreting various inflammatory molecules, including interleukin (IL-6) and tumor necrosis factor-α (TNFα)." (PMID 31165723, 2019). "The lower expression of TNF-α observed during the early stage of infection of trophoblasts with the high-virulence isolate Nc-Spain7 supports the hypothesis that this isolate may modify by yet unknown mechanisms the pro-inflammatory response by trophoblast cells." (PMID 31068227, 2019). "The use of Bokashi preparation as feed additives also resulted in increased concentrations of pro-inflammatory cytokines TNF-α and IL-6, which increase the protective capacity of the colostrum by stimulating cellular immune mechanisms protecting the mother and neonates against infection." (PMID 29305686, 2019). "Hence, the blocking of enhanced proinflammatory cytokine TNF-α might reduce the pathology due to the primary and secondary infections." (PMID 31466307, 2019). "Hepatic inflammation is triggered in response to infection and tissue injury and is characterized by the recruitment of innate immune cells and the production of pro-inflammatory cytokines, such as tumor necrosis factor alpha (TNF-α), interleukin (IL)-1 and IL-613." (PMID 31110285, 2019).
infection (continued). "Furthermore, by combining TNF-α responses with IL-10 and IL-1ra responses, patients could be accurately classified into one of these two infection states." (PMID 31024518, 2019). "Moreover, the presence of TNF-α inhibited infection of Vero cells infected with CHIKV LR2006-OPY1 as measured by reduced CPE in the monolayers with as little as 5 pg/ml, and an IC50 of 14.49 ± 2.99 as determined by nonlinear regression using GraphPad Prism software." (PMID 31026260, 2019). "Moreover, microarray assay in combination with CRNG interference and overexpression showed that the differential genes such as ANPEP, KITLG, STAT5A, FOXP3, miR-451, IL-2, IL-10, IL-6, and TNF-α are mainly involved in viral and pathogens infection and the immune-inflammatory responses in PK-15 cells." (PMID 31178726, 2019). "Perhaps CD8+ T cells might have undertaken TNF-α production during later stages of infection." (PMID 31885849, 2019). "TNF-α blockers therapy could modulate the immunological response to a less effective control of the parasite, hence allowing the infection reactivation or more evident disease expression of newly acquired infections." (PMID 31469834, 2019). "Although speculative, it is possible that prior to the IHC detectable stage of CWD infection, an initial increase in TNF production occurs in response to initial infection, which overtime becomes detrimental to deer whose response is to down‐regulate TNF as identified in this study." (PMID 31788200, 2019). "In conclusion, TNF-α may be an important factor in the early anti-inflammatory effects of infection, and it may have the necessary protective effect in the chronic phase of infection." (PMID 31072917, 2019). "Thus, pattern recognition is essential for controlling mycobacterial growth by regulating optimum levels of the TNF/IL-10 ratio during the period of infection, while miR-21 levels could counterbalance or impair an adequate antimicrobial response." (PMID 29755459, 2018). "Subsequently, a comparative infection model using BALB/c, C57Bl/6, C3H/HeN, and CBA/Ca mice showed that while TNF production per se was required for proper parasitaemia control, infected mice responded to TNF-associated inflammation with the shedding of TNF-R2 receptors." (PMID 30333827, 2018). "Furthermore, increase in pro-inflammatory plasmatic cytokines, IL-6, IFN-γ, and TNF-α together with the presence of activated macrophage in both blood and spleen could help in resolution of infection with B. microti." (PMID 29445365, 2018). "Additionally, SCID mice showed impaired clearance at day 3 post-infection when treated with TNF neutralizing antibodies, and by day 5 most anti-TNF treated animals had succumbed to infection, showing a requirement for TNF in both the innate and adaptive arms of the immune response." (PMID 29438281, 2018). "However, TNF-α treatment increased the burden of both vDNA and RNA in PM, suggesting that further activation of transcription, presumably through NF-κB, induced progeny virus production and infection of new cells." (PMID 29879225, 2018). "However, multivariate analysis, demonstrated no significant increased risk of infection (OR 0.99, 95% CI 0.64–1.53) due to anti-TNF therapy after controlling for factors such as disease duration, severity and concurrent corticosteroid and immunomodulator use." (PMID 30065229, 2018). "Infection control as a function of a Th1 response occurs through the elimination of parasites in macrophages by microbicidal mechanisms mediated by reactive oxygen species, such as nitric oxide (NO); in addition, TNF-α acts synergistically with IFN-γ to increase NO production by macrophages." (PMID 30046335, 2018). "However, correlation between parasite load and the production of TNF-α by spleen extracts of dogs naturally infected has been documented, and according to the authors, it may represent an important marker for infection evolution." (PMID 30237985, 2018).
infection (continued). "Furthermore, IL-15 secreted by phagocytic monocytes during the innate response is a growth factor for γδ T cells, promotes cytotoxicity by NK cells, and stimulates their secretion of INFγ and TNFα, thereby linking innate and adaptive immunity during infection with M. tuberculosis." (PMID 29770360, 2018). "It is tempting to hypothesize that, at early infection (8h in this study), INPPD5 is downregulated by mmu-miR-155-5p, leading to the production of major pro-inflammatory cytokines, such as 1L-1α and TNF-α, previously observed in macrophages, as a first response to infection by Leptospira." (PMID 29979677, 2018). "Although reports show that marginal-zone development is impaired and fewer marginal-zone macrophages are present in TNF-deficient and p55-TNFR (tumor necrosis factor receptor 1 [TNFR1])-deficient mice, other reports suggest that TNF triggers marginal-zone macrophage depletion after infection." (PMID 29142134, 2018). "Since TNF-α signaling is key in both the acute infection and CCC, we added TNFA and TNF-receptor alpha (TNFRSF1A) to this table, even though TNFA was only assessed in association studies (120–123, 132, 133, ), and TNFRSF1A only in knockout infection experiments." (PMID 30559742, 2018). "Thus, we speculate that serum TNF-α and IFN-γ levels in pediatric MPP may be potential diagnostic markers of infection by this pathogen." (PMID 30275916, 2018). "Furthermore, Vitamin D has also been shown to stimulate the expression of several cytokines, such as Tumor Necrosis Factor α (TNFα), that regulate both the recruitment of inflammatory cells to the area of infection and the activation of macrophage and T cell functions." (PMID 30326825, 2018). "This phenotype was reversed by reconstitution of the infection site with in vitro differentiated wild-type, but not TNF-deficient MCs, which has been interpreted to suggest that MCs promote recruitment and retention of lymphocytes in LNs draining infected tissues by release of TNF." (PMID 30210490, 2018). "That VIP is protective in vitro, suggests that the decreased levels of VIP occurring in the colonic epithelial cells during infection may lead to that the infection induced expression of TNFα and IFNγ inflict even greater damage than what might have occurred otherwise." (PMID 30252907, 2018). "TNF-α is a diverse cytokine which has been shown to functionally aid in the formation and maintenance of a granuloma as well as to play a critical role in the host defense against M. tuberculosis in both the acute phase and the chronic phase of infection (42, –, 44)." (PMID 30126957, 2018). "However, changes in serum levels of TNF-α and IFN-γ may be transient during an acute infection and we simply missed the window of time to measure any fluctuations in TNF-α or IFN-γ from baseline levels in this animal." (PMID 29304133, 2018). "Interestingly, tolerance may also be a result of certain infections, since adenoviral infection of mice has been described to yield a tolerance-like condition towards TNF treatment." (PMID 29250561, 2017). "The inflammatory nature of the infection means that C. rodentium interactions with IECs take place in an environment rich in cytokines (e.g., interleukin-18 [IL-18], IL-22, IL-6, IL-1β, tumor necrosis factor alpha [TNF-α], interferon-γ) and infiltrating immune cells." (PMID 28988824, 2017). "Caution should be used before starting TNF-α and underlying infection should be ruled out." (PMID 29065902, 2017). "Our studies found that infection alone induced an inflammatory response characterized by a high level of inflammatory cells associated with genital tract inflammation (neutrophils and CD8, TNF-α producing cells) compared to that of mice vaccinated with PmpG-vaults." (PMID 28106821, 2017). "Therefore, IFNγ-stimulated infected astrocytes are potential sources of TNF, which may facilitate astrocyte infection." (PMID 28877735, 2017).